PRMT6 (protein arginine methyltransferase 6)
Diseases named in the same sentence as PRMT6 in open-access papers (continued):
Sharing a sentence is not in itself a finding about the gene and the disease.
tumor (continued). "This concept was underscored by our in vivo results, wherein the deletion of PRMT6 significantly curtailed tumor metastasis." (PMID 37813837, 2023). "Our in vivo experiments provided compelling evidence that deficiency in STAT3 R729me2a significantly curbed the metastatic potential of BRCA cells, thereby reinforcing the dependence of PRMT6-mediated tumor metastasis on STAT3 R729me2a." (PMID 37813837, 2023). "The tumor-promoting effect of PRMT6 is also seen in other systems, such as the blood system, and can be seen in leukemia." (PMID 35311114, 2022). "In this review, we will summarize some recent studies on PRMT family, and focus on the different roles of PRMT6 in tumor." (PMID 35311114, 2022). "It was also found that the transcriptional co-repressors PRMT5 and PRMT6 were overexpressed in hematocarcinoma and inhibited the expression level of tumor suppressor genes." (PMID 35311114, 2022). "The silencing of PRMT6 promotes tumor initiation, metastasis, and anti-therapeutic potential in HCC cell lines and patient-derived organoids." (PMID 35311114, 2022). "PRMT6 also promoted tumor progression by facilitating macrophage differentiation to the M2 phenotype rather than the M1 phenotype, and supporting tumor neoangiogenesis." (PMID 35493527, 2022). "Mice lacking PPARα had increased expression of DNMT1 and protein arginine methyltransferase 6 (PRMT6), resulting in methylation of the tumour suppressor genes P21 and p27, respectively." (PMID 34638914, 2021). "PRMT6 downregulates these tumor suppressors by generating the repressive H3R2me2a modifications in their promoters and other regulatory regions." (PMID 34575100, 2021). "PRMT6 interacts with interleukin enhancer binding protein 2 (ILF2) and activates the tumor associated macrophages." (PMID 34575100, 2021). "Based on these reports, we examined the inter-relationships between PRMT6 and two tumor suppressor expressions as well as levels of H3R2 methylation in three CRC cells." (PMID 29507670, 2018). "We found that the expression levels of PRMT1, PRMT2, PRMT4, and PRMT6 are positively correlated with the tumor grades." (PMID 30382083, 2018). "A number of histone methyltransferases, including Setd3, Setd5, Suv39h2, Smyd3, Prmt3, Prmt6, Nsd1, and Nsd2, were up-regulated in metastases compared to disseminated tumor cells or primary tumors." (PMID 23520493, 2013). "These and our findings that enzyme activities of CARM1/PRMT4 and PRMT6 are capable of regulating tumor suppressor activity and cellular proliferation raise questions of a common meaning for cellular metabolism." (PMID 22916108, 2012). "We found a significant overexpression of PRMT6 in 54.1% of tumour samples as compared with 43.9% in normal breast epithelium (examples are shown on the right)." (PMID 22987071, 2012). "PRMT6 inhibitor significantly inhibited tumor growth in two patient-derived xenograft models." (PMID 41862993, 2026). "PRMT6 contributes to tumor proliferation by regulating transcription and mitotic signaling." (PMID 41204384, 2025). "The sphere formation assay confirmed that PRMT6 overexpression reduced the inhibition of tumor sphere formation caused by RBM39 knockout, while the combination of MS023 and RBM39 knockout led to the formation of even fewer tumor spheres." (PMID 40465651, 2025). "The results indicate that although PRMT6-mediated RBM39 methylation promoted the growth and metastasis of NSCLC cells, PRMT6 may also play a pro-tumor role through other target proteins when RBM39 is knocked out." (PMID 40465651, 2025). "In the TCGA and CGGA databases, we found that PRMT6 expression increases with tumor grade." (PMID 38637831, 2024). "Notably, STAT3R729me2a plays an important role also in PRMT6-mediated tumor metastasis and PRMT6 inhibition is able to reduce metastasis." (PMID 39680066, 2024). "Furthermore, tumor xenograft experiment was adopted to evaluate the in vivo effect of PRMT6-mediated p62 ADMA." (PMID 38994016, 2024).
tumor (continued). "Hence, PRMT6 possesses transcriptional repression and transcriptional activation functions, thus, additional research is needed to elucidate the role and molecular mechanisms of PRMT6 in tumor progression, and to develop antitumor strategies." (PMID 36941223, 2023). "Having established PRMT6’s capacity to regulate the IL-6/STAT3 signaling pathway—an essential player in tumor metastasis—it was imperative to delve deeper into whether PRMT6-mediated tumor metastasis hinged on the IL-6/STAT3 signaling pathway." (PMID 37813837, 2023). "Increasing evidence indicates that PRMT6 plays a tumor mediator involved in human malignancies." (PMID 36792756, 2023). "Furthermore, the in vitro findings in our study underscored that PRMT6’s mediation of tumor metastasis hinged on STAT3 phosphorylation." (PMID 37813837, 2023). "In addition, studies have confirmed that PRMT6 is involved in regulating drug resistance of tumor cells." (PMID 35311114, 2022). "Therefore, the regulatory axis of PRMT6-ERK-PKM2 has a mechanistic association with tumorigenicity of HCC, sorafenib resistance, and Warburg effect of tumor cells, and is an important determinant factor." (PMID 35311114, 2022). "As PRMT6 has been found to have the ability to regulate cell cycle and inhibit the expression of tumor suppressor genes in a variety of tumors, with oncogene-like properties, it is often found to be significantly overexpressed in tumor tissues, and is associated with poor prognosis." (PMID 35311114, 2022). "The potential clinical relevance of restoring AR expression in Sh-PRMT6 PC-3 suggests that PRMT6 inhibition may re-sensitize androgen-insensitive tumor cells to ADT, providing a new approach for the treatment of castration-resistant prostate cancer (CRPC)." (PMID 35311114, 2022). "The role of PRMT6 is controversial as its expression is different in different tumor types." (PMID 33670008, 2021). "In addition, the downregulation of PRMT6 promotes the autophagy and contributes to the tumorigenicity and cell survival in the tumor microenvironment." (PMID 34575100, 2021). "PRMT6-inhibition leads to a reduced tumorigenic potential because of up-regulation of p21, and it would, therefore, be an ideal drug target to slow down the growth of rapidly dividing tumours." (PMID 22987071, 2012). "We stained an additional 215 samples and found 58.6% of tumours expressing high levels of PRMT6." (PMID 22987071, 2012). "It is hypothesized that PRMT6 may directly regulate the function, differentiation, or exhaustion of T cells through methylation modification, thereby influencing the intensity of anti-tumor immune responses." (PMID 41154773, 2025). "PRMT6 can also hinder the recruitment of the auxiliary factor UHRF1 of DNA methyltransferase DNMT1 to chromatin through the methylation modification of histone H3R2me2a, thereby affecting the methylation of DNA and causing a widespread state of DNA hypomethylation in tumor cells." (PMID 38637831, 2024). "A study showed that PRMT6 promotes PKM2 nuclear translocation, leading to increased aerobic glycolysis in HCC, while the addition of 2-DG (a well-known inhibitor of glycolysis) sufficiently reverses PRMT6 deficiency-mediated tumor progression and sorafenib resistance." (PMID 37566009, 2023). "In addition, we clarified the tumor-related arginine methyltransferase PRMT6 could interact with MCM7 in the present study." (PMID 21619671, 2011). "PRMT6 promotes EMC cell migration and proliferation by activating the AKT/mTOR signaling pathway, thereby contributing to tumor progression." (PMID 41154773, 2025). "PRMT6 acts as an oncogene in LUAD by epigenetically repressing p18 expression, which impedes the G1/S phase transition and facilitates tumor cell proliferation in both in vitro and in vivo models." (PMID 41154773, 2025). "In conclusion, PRMT6-mediated RBM39 methylation reverses Indisulam-induced oncogene mis-splicing and diminishes its anti-tumor activity." (PMID 40465651, 2025).
tumor (continued). "In the context of Neu-induced carcinogenesis, overexpression of PRMT1 and PRMT6 significantly accelerated breast tumor onset, while CARM1 increased tumor progression only at tumorigenesis." (PMID 35311114, 2022). "PRMT6 is observed up-regulated in CRC tissues, its activity plays a key role in tumor cell differentiation." (PMID 35311114, 2022). "With the identification of PRMT6 and CARM1 as inhibitors of p21 and p27 a novel link between the methylation cycle and tumor suppression is pointed out." (PMID 22916108, 2012). "Interestingly, for those samples for which we had clinical information regarding the tumour stage (n = 166), we observed positive correlation (P = 0.019) between PRMT6 up-regulation and tumour stage, suggesting that more aggressive tumours might benefit from PRMT6 overexpression." (PMID 22987071, 2012). "Other immunohistochemical tumor markers, such as CD45RO+ and PRMT6, can also be detected by AI." (PMID 40075729, 2025). "PRMT6 suppresses TSP-1 transcription by altering H3R2 and H3K4 methylation at its promoter in breast, prostate, and osteosarcoma cells, thereby facilitating tumor angiogenesis." (PMID 41204384, 2025). "Our current research finds PRMT6 upregulated in GBM, enhancing tumor malignancy." (PMID 38637831, 2024). "To investigate the role of PRMT in the development of HNSC, we first analyzed the expression levels of PRMT family members (PRMT1-PRMT9) in tumors using TCGA data, and we found that PRMT6 and PRMT9, the other PRMT family members, had significantly elevated expression in tumor tissues." (PMID 38663941, 2024). "Notably, PRMT1, PRMT2, PRMT3, and PRMT7 exhibited upregulation, while PRMT5, PRMT6, and PRMT8 displayed downregulation in tumor." (PMID 37781030, 2023). "PRMT6 expression increased by more than 1.5-fold in seven tumor samples matched with adjacent noncancerous tissues from the same patients." (PMID 29507670, 2018). "Consistently with our in vitro data, PRMT6 sh-2 KD cells did not form primary tumours in any of the injected animals." (PMID 22987071, 2012). "Although the comprehensive mechanisms of the PRMT6/PARP1/CRL4B complex remain to be fully elucidated, our study reveals that the PRMT6/PARP1/CRL4B complex transcriptionally represses the core clock gene PER3, interrupting circadian clock oscillation, thereby promoting tumor progression." (PMID 36941223, 2023). "The conflicting impact of PRMT6 might be attributed to the regulation of autophagy processes triggered by the progressive decline in PRMT6 expression during HCC tumorigenesis and progression, thereby resulting in bidirectional effects, including both tumor development and suppression." (PMID 37627211, 2023). "To identify the PRMT responsible for arginine methylation of NONO in CRC cells, we examined PRMT1, PRMT3, PRMT4, PRMT5, PRMT6, and PRMT8 mRNA and protein levels in paired tumor and adjacent normal tissues." (PMID 33420374, 2021).
infection (3 papers, 2013 to 2018). The state of being infected such as from the introduction of a foreign agent such as serum, vaccine, antigenic substance or organism. "When viral input was normalized by QPCR or RT activity, WT PRMT6 restriction was carried over to a second cycle of infection, as shown in a TZM-bl infectivity assay." (PMID 23866860, 2013).
inflammation (2 papers, 2019 to 2021). Aberrant reaction of the microcirculation characterized by movement of fluid and leukocytes from the blood into extravascular tissues. "Our previous mouse model and in vitro studies revealed that PRMT6 exerts a negative effect on CS-induced pulmonary inflammation through H3R2me2a, while overexpression of PRMT6 inhibits CS-induced inflammation." (PMID 31711545, 2019).
PRMT6 also shares sentences with these, for which no sentence is quoted: tuberculosis (3 papers); liver (2); mesothelioma (2); non-small cell lung carcinoma (2); fibrosis (1); hearing loss (1); Insulin resistance (1); kidney tumor (1); male infertility (1); spinal cord injury (1).